FGFR4 (fibroblast growth factor receptor 4)
Diseases named in the same sentence as FGFR4 in open-access papers (continued):
Sharing a sentence is not in itself a finding about the gene and the disease.
tumor (continued). "FGFR4, a protein recognized by MS for its crucial involvement in enhancing the malignant phenotype of cancer cells and affecting the tumor microenvironment, captured our attention and was pinpointed as a potential protein interacting with cLMNB1." (PMID 41213916, 2025). "Meanwhile in NSD tumours, EGFR mutations and copy number gains, in addition to the gains of additional growth factor receptor genes PDGFRB and FGFR4, suggest that this pathway is activated via a different mechanism." (PMID 41509216, 2025). "When we collected the tumors and examined the levels of protein expression, we found that SORL1 knockdown led to the downregulation of both EGFR and FGFR4 in the tumor samples." (PMID 39858026, 2025). "Ninety-six percent of 53 IHC FGF19-positive tumours were assessed for FGFR4 and KLB mRNA expression." (PMID 40205008, 2025). "Treatment with BLU9931, an FGFR4 inhibitor, attenuated tumor progression, and co-treatment with the CXCR3 inhibitor AMG487 further enhanced this inhibitory effect, highlighting the synergistic function of the two inhibitors." (PMID 40447617, 2025). "To determine if HNF1A and FGFR4 expression are widely associated in PDAC patients, we utilized multispectral immunofluorescence staining of a tumor microarray of 220 PDAC patient samples." (PMID 40731412, 2025). "The DOX + Osi group showed the largest tumor regression extent, while high FGFR4 expression counteracted this effect." (PMID 41213916, 2025). "It activates high-affinity receptor FGFR4 in a paracrine manner, thereby driving malignant tumor progression." (PMID 41551579, 2025). "We found that expression of HNF1A and FGFR4 were significantly higher in PDAC cell lines of a metastatic/ascites origin versus primary tumor origin." (PMID 40731412, 2025). "Mechanistically, FGF19 promotes EMT, a critical process for tumor invasion and dissemination, through FGFR4-mediated activation of key signaling pathways." (PMID 41002393, 2025). "The change of FGFR4 is related to higher level of tumor mutation burden (TMB) in tumor stroma, more CD8+ T cells and higher M1/M2 ratio of TAMs in tumor center and stroma." (PMID 39927632, 2025). "Molecular validation revealed a marked reduction of FGF17 protein levels in tumor samples from the shFGF17 group (p < 0.001), accompanied by concurrent suppression of its receptor FGFR4 and downstream p-MEK5 and p-ERK5 (Thr218/Tyr220) (p < 0.05)." (PMID 41551579, 2025). "As prior research suggested, the inhibition or downregulation of EGFR or FGFR4 can lead to tumor suppression." (PMID 39858026, 2025). "FGF19-positive patients showed radiographic tumour shrinkage and a trend for better responses to FGFR4 inhibitors." (PMID 40205008, 2025). "It has been observed that lenvatinib inhibits the angiogenic factor in the tumor microenvironment and blocks fibroblast growth factor receptor 4 (FGFR4)." (PMID 38380330, 2024). "T-cells expressing dual targeting FGFR4.28HTM.28z-CD276.8HTM.BBz BiCisCAR demonstrated the highest level of tumor killing, T-cell expansion, persistence, and lowest degree of exhaustion." (PMID 39043633, 2024). "Hub genes with high centrality, including PTK6, FGFR3, and FGFR4, which have been recognized as therapeutic targets in tumor treatment." (PMID 38347596, 2024). "We detected expression of FGFR1 and FGFR2 in tumor organoids, with higher levels in embryonal than fetal organoids, while FGFR4 was exclusively expressed in fetal tumor organoids." (PMID 39567475, 2024). "In summary, the results of this study suggest that the CAR-T cells derived from high specificity and high affinity Nbs, targeting FGFR4, exhibited significantly enhanced anti-tumor efficacy in vitro and in vivo." (PMID 38610029, 2024). "The histopathological and molecular features of the tumor, including mutations in ABL1, CCND1, CSF1R, FGFR4, KDR, and MALAT1-GLI1 fusion, are elucidated and discussed in the context of diagnostic, prognostic, and therapeutic considerations." (PMID 38732067, 2024).
tumor (continued). "Previous studies have found that fibroblast growth factor receptor 4 (FGFR4) plays a crucial role in tumor development and metastasis." (PMID 39658878, 2024). "The FGFR4.28HTM.28z-CD276.8HTM.BBz BiCisCAR T-cells demonstrated superior tumor-killing activity than those of FGFR4.28HTM.BBz-CD276.8HTM.BBz in vitro." (PMID 39043633, 2024). "It plays a fundamental role in cancer by participating in signaling and tumor progression and presenting some small molecular inhibitors that target FGFR4." (PMID 38540215, 2024). "FGFR4 was also reported for its important role in tumor progression, oncogenesis, and the development of treatment resistance." (PMID 38542291, 2024). "Bisulfite sequencing of Hrasls, Ret, Nr4a1, and Fgfr4 revealed inter- and intra-tumor heterogeneity in the DNA methylation of promoter regions." (PMID 38297314, 2024). "An intriguing observation is the expression of FGFR4 in the fetal tumor cells and its ligand FGF19 in the embryonal tumor cells, suggesting crosstalk between the two subtypes." (PMID 39567475, 2024). "Despite its potent antitumor activities, this FGFR4 CAR’s therapeutic effect is unclear in stress conditions such as with a low infused CAR T-cells to tumor burden ratio." (PMID 39043633, 2024). "When tested in vivo, T-cells expressing FGFR4.28HTM.28z-CD276.8HTM.BBz BiCisCAR exhibited faster tumor eradication, increased persistence, and reduced expression of exhaustion markers such as CD39, PD-1, and LAG-3." (PMID 39043633, 2024). "FGFR4.28HTM.BBz showed similar in vitro tumor-killing ability and cytokine production as the original FGFR4.8HTM.BBz CAR T-cells, but exhibited enhanced in vivo antitumor activity." (PMID 39043633, 2024). "This is in line with our data, as we also detected a gain of chromosome 5 containing the FGFR4 gene in the tumor of one patient by OncoScan analysis." (PMID 39411551, 2024). "sEV–vWF‐activated endothelial FGF2 promotes tumor aggressiveness via positive feedback signaling toward HCC cells through an activated FGFR4‐ERK signaling axis." (PMID 37387563, 2023). "Surprisingly, disrupting FGF19 via gene silencing or the FGFR4 inhibitor BLU9931 recapitulates most phenotypes observed with HMGA1 deficiency, decreasing tumor growth and formation of a desmoplastic stroma in mouse models of PDAC." (PMID 36919699, 2023). "FGFR4 activates the PI3K/AKT/HIF1α pathway to promote transcription of homeobox B5, which in turn upregulates FGFR4, thereby promoting tumor cell metastasis." (PMID 37750089, 2023). "One recent mouse study demonstrated that FGFR4 contributes to tumor proliferation and invasion through activation by TGF-β1 in the extracellular signal-related kinase (ERK) pathway; silencing FGFR4 expression was found to inhibit this activity." (PMID 36768686, 2023). "Our study demonstrated that the sEV–vWF/FGF2/FGFR4 cascade mediates tumor–endothelial cellular communication in HCC." (PMID 37387563, 2023). "In a previous study, the multi-kinase inhibitor ponatinib was shown to inhibit mutant FGFR4-driven RMS tumor growth in mice." (PMID 37627061, 2023). "This suggests that although futibatinib is pharmacodynamically active in suppressing FGFR4 signaling in the tumor, it is ineffective as a monotherapy for RMS, possibly due to adaptive resistance mechanisms to FGFR4 inhibition." (PMID 37627061, 2023). "FGFR4 is highest expressed in cholangiocytes with lower expression in hepatocytes in both in non-tumor and tumor tissue." (PMID 37770545, 2023). "Further, IHC assay was used to evaluate the protein levels of Fgfr3 and Fgfr4 in tumour sections derived from WT and Kdm6a CKO mouse HCC tissues." (PMID 37846441, 2023). "The number of endothelial cells and activation of FGFR4 in tumorous tissues was significantly correlated." (PMID 37387563, 2023).
tumor (continued). "With the new construct, the anti-FGFR4 CAR-T cells combined with a multi-drug approach targeting the myeloid cells responsible for the immunosuppressive microenvironment showed high tumor elimination capacity in orthotopic mouse models." (PMID 37766309, 2023). "A comprehensive analysis of ccRCC genetic alterations revealed that 60% of ccRCC tumours harboured a copy number amplification of FGFR4." (PMID 36803783, 2023). "Fibroblast growth factor receptors (FGFRs) comprising FGFR1,FGFR2,FGFR3 and FGFR4 have been reported to play important roles in the regulation of the main target genes of lenvatinib and control tumour metabolism in many cancer types including HCC." (PMID 37846441, 2023). "Our data showed that depletion of METTL16 by GampeR ASO enhances the tumor inhibitory effect of the FGFR4 inhibitor BLU-554." (PMID 37817227, 2023). "In colon cancer tissues, tumor‐associated fibroblasts generate chemokine ligand 2, which acts on its receptor on the tumor surface to enhance the transcription of FGFR4 in an Ets‐1‐dependent manner, thereby activating the β‐catenin pathway to lead to EMT." (PMID 37750089, 2023). "FGF and FGFR are up-regulated in various tumor tissues, and FGFR4 activates a downstream oncogenic signaling pathway to promote cancer development." (PMID 37895197, 2023). "Accordingly, putative target genes of HNF1A were significantly enriched in FGFR4 high tumours of the ICGC cohort." (PMID 35963908, 2022). "ROC curve showed the accuracy of the FGFRs in tumor diagnosis, among which FGFR4 had the highest ROC value." (PMID 36147913, 2022). "The expression of FGFR3 and FGFR4 were significantly higher in tumor than in normal samples in GC (p<0.001)." (PMID 36147913, 2022). "For example, gene mutation biomarkers such as POLE, ARID1, and FGFR4 increase the TMB level, expression of PD-L1, and activation of the cellular immunity CD8+ tumor infiltration level." (PMID 35359393, 2022). "The involvement of FGFR4 in cellular mechanisms of tumour aggressiveness suggests its driver role in cancer and consequently its potential as a therapeutic target." (PMID 35194944, 2022). "Of note, the organoid culture with the highest basal-like/squamous identity (PDA9-O) showed the lowest expression of FGFR4, thus representing a model for FGFR4low basal-like tumours." (PMID 35963908, 2022). "An extended panel of primary surgical specimen-derived and immortalized GBM (stem)cell models and original tumor tissues were screened for FGFR4 expression." (PMID 35484633, 2022). "This is well in agreement with the massive inhibitory effect of FGFR4-KD(K504M) expression on wound-healing capacity, reflecting in many aspects the invasive tumor leading edge." (PMID 35484633, 2022). "Accordingly, we detected shorter overall survival of the FGFR4high patient subgroups from several datasets, and FGFR4-KD(K504M) tumor-bearing mice survived significantly longer as compared to endogenously FGFR4high control xenografts." (PMID 35484633, 2022). "Compared with cetuximab, FGFR4 inhibitor (BLU9931) combined with cetuximab has a stronger anti-tumor effect." (PMID 35740594, 2022). "When combined with an FGFR4 inhibitor, the anti-tumor effect of anti-PD-1 treatment increased significantly in a GC xenograft mouse model with overexpressed FGFR4." (PMID 36147913, 2022). "Here, we provide multiple lines of evidence that FGFR4 expression is restricted to epithelial cells in both normal and diseased pancreata, selectively elevated in classical tumours, and correlated with better outcomes." (PMID 35963908, 2022). "We found the significant enrichment of gene sets related to the PI3K/AKT, ERBB, Axon guidance, and RAS signalling pathways in PDAC cells depleted for FGFR4 as well as in the FGFR4low tumours of both the ICGC and PanCuRx cohorts." (PMID 35963908, 2022).
tumor (continued). "It has been discovered that patients showing a strong response or complete response to nCRT have a significantly lower expression of FGFR4 in their tumor tissue, whereas patients with high FGFR4 expression correlated with poor radiosensitivity (p = 0.04)." (PMID 35682714, 2022). "FGF401 (roblitinib) is a reversible, covalent, potent and highly selective FGFR4 inhibitor with antitumor activity in FGF19/FGFR4-dependent tumor models." (PMID 35655320, 2022). "Our findings revealed significantly decreased FGFR1 and FGFR4 mRNA expression in tumor tissue compared with tumor-adjacent normal tissue." (PMID 36142417, 2022). "FGFR1 and FGFR4 gene expression levels were significantly decreased in tumor samples (n = 20) compared with tumor-adjacent normal tissue (n = 20): FGFR1 (p = 0.0002) and FGFR4 (p = 0.000001)." (PMID 36142417, 2022). "FGFR4 protein expression was also orthogonally detected by immunohistochemistry (IHC) of HCC patient tumor samples in the human pathology atlas project." (PMID 35433463, 2022). "FGFR4 inactivation in the FGFR4high BTL1528 model resulted in significantly reduced tumor volumes and longer overall survival times of the animals." (PMID 35484633, 2022). "Overall, compound 6O, a novel derivative of aminodimethylpyrimidinol, was a selective FGFR4 kinase inhibitor blocking HCC tumour growth." (PMID 35296193, 2022). "FGFR4 can promote tumor cell invasion, proliferation and development of resistance, while FGFR4 inhibitors or silencing using siRNA can attenuate or reverse these effects." (PMID 35513870, 2022). "Low expression of FGFR4 was observed in 23% (22/97) of cases and was significantly enriched in high grade tumours." (PMID 35963908, 2022). "In terms of function, overexpression of FGFR4 promotes tumor development, cell migration, and invasion." (PMID 36147913, 2022). "To corroborate our findings, we interrogated RNA-seq from patients’ tissues and found that ZBED2 is the gene whose expression is more prominent in FGFR4 low tumours of the ICGC cohort." (PMID 35963908, 2022). "In a recent study, lenvatinib reduced the tumor PD-L1 level and Treg differentiation to improve anti-PD-1 efficacy by blocking FGFR4." (PMID 35655320, 2022). "FGFR1 and FGFR4 mRNA levels are significantly decreased in Sq-NSCLC tissue compared with tumor-adjacent normal tissue." (PMID 36142417, 2022). "Nevertheless, FGFR1 and FGFR4 expression levels were increased and approximated to expression in tumor-adjacent normal tissue (fold-change, ~1) in individual tumor samples: 3 (15%) and 1 (5%), respectively." (PMID 36142417, 2022). "Although tumor growth was obviously inhibited by the sorafenib and selective FGFR4 inhibitor treatment, it was further suppressed by the co-treatment of sorafenib and a selective FGFR4 inhibitor." (PMID 33674622, 2021). "They cite a work where DEN-mediated HCC induction in FGFR4 knock-out mice promoted tumor growth while spontaneous tumor formation remained unaltered." (PMID 34200439, 2021). "The result suggests that inflammatory cytokines, especially IL-1β, can influence the activation of the FGF19/FGFR4 signaling pathway in the tumor microenvironment." (PMID 33981224, 2021). "Our study demonstrated that robust inhibition of FGF19/FGFR4 is of importance for the exertion of anti-tumor effects by MKIs." (PMID 33674622, 2021). "We have demonstrated that blockade of tumor-derived FGF19/FGFR4 signaling represents a promoting therapeutic strategy to preferentially target FGF19-driven HNSCC." (PMID 33691750, 2021). "So, it is expected that overexpression of FGF19, β-klotho, and/or FGFR4 in tumor cells is related to the development and progression of HCC." (PMID 34200439, 2021). "Abnormal gene expression of FGFR4 with its ligand FGF19 has been determined as a vital factor in tumor growth." (PMID 33981224, 2021). "The depletion of both FGF19 and FGFR4 increases the sensitivity of tumor cells to sorafenib, resulting in enhanced apoptosis and decreased viability." (PMID 33802841, 2021).
tumor (continued). "The HCI-009 PDX model exhibiting high FGFR4 expression and phosphorylation was subjected to treatment with a FGFR4 inhibitor, BLU9931 to characterize effects on tumor growth in vivo, cell proliferation and FGFR4 downstream signaling." (PMID 34344433, 2021). "Here, the authors observed that overexpression of FGF21 delays DEN-induced tumor formation in mice, and they attributed it to the activation of hepatocyte’s FGFR4 in an initial stage." (PMID 34200439, 2021). "Recently, FGFR4 has received a great deal of attention from researchers due to its roles in tumorigenesis and anti-tumor therapy resistance in different cancers." (PMID 34400727, 2021). "Suppression of the expression of FGFR4 and its ligand or the impairment of its downstream activation has been known as the main reason for tumor growth." (PMID 33981224, 2021). "FGFR4 plays a critical role in embryonic development, tissue repair, tumour angiogenesis and progression." (PMID 34021172, 2021). "Considering the most representative variants shared by tumor fragments and plasma of dogs, we identified important gene variations in ATM (C > A mutation), CCNE1 (G > C), FGFR4 (C > T), and GATA3 (G > A and C > CT)." (PMID 34680380, 2021). "We found that the most aggressive subclone YTN16 expressed FGFR4 at high levels and that disruption or inhibition of FGFR4 suppressed tumor growth both in a subcutaneous and peritoneal dissemination model." (PMID 35008270, 2021). "FGFR4 overexpression has also been found as a frequent event in ARMS cell lines (3/3 tested) as well as in tumor samples, with 34/39 (87.2%) samples showing an immunohistochemical signal in more than 25% of the cells." (PMID 34204560, 2021). "Altogether, these data indicate that FGFR4 activation is related to tumor progression suppression and with the protection of steatotic and non-steatotic livers against damage and regenerative failure." (PMID 34200439, 2021). "Herein, this review discusses the characteristics of FGFR4 signaling in tumor progression and features some small molecular inhibitors that target FGFR4, intending to increase our understanding of this pathway." (PMID 33981224, 2021). "On average, the expression of FGFR1 mRNA appeared to be lower than that of FGFR4 in tumor tissue compared to peritumoral tissue." (PMID 33119860, 2021). "In fact, over-expression and mutational activation of FGFR4 has been reported in RMS, promoting tumour progression." (PMID 33916788, 2021). "Treatment with this TKI also inhibited tumor growth in murine RMS xenograft models from cell lines expressing mutant FGFR4." (PMID 34204560, 2021). "According to Cancer Genome Interpreter (CGI) analysis, alterations in SETD2, BAP1, FLT4 and PTEN genes were reported as known drivers in several tumor types, and events in FGFR4 and NSD1 genes were classified as predicted drivers." (PMID 33668731, 2021). "To examine the anti-tumor effects of MKIs and a selective FGFR4 inhibitor in vivo, we conducted xenograft transplantation using Non-obese diabetic/severe combined immunodeficiency (NOD/SCID) mice." (PMID 33674622, 2021). "Multiple FGFR4 inhibitors can be applied to treat cancers where FGFR4 signaling is responsible for tumor development." (PMID 33981224, 2021). "For 23 cases, the same level of FGFR1 and/or FGFR4 expression was detected between the primitive tumor and the recurrences." (PMID 33092134, 2020). "Specifically, FGFR4 can act directly on tumor cells to influence paracrine signaling, angiogenesis, and immune escape, normalizing the tumor microenvironment." (PMID 33034614, 2020). "Higher expression of FGF19 in HCCs promotes tumor cell survival and has antiapoptotic effects that are exerted through the FGFR4-glycogen synthase kinase (GSK)3β-Nrf2 signaling cascade." (PMID 32104677, 2020). "The FGFR4 Arg388-variant enhances STAT3 signaling, promotes tumor progression, and is associated with poor prognosis of multiple cancers." (PMID 32154250, 2020).